IL1B (interleukin 1 beta)
Diseases named in the same sentence as IL1B in open-access papers (continued):
Sharing a sentence is not in itself a finding about the gene and the disease.
infection (continued). "The release of pro-inflammatory cytokines was determined in BAL samples collected at day 7 after infection, and concentrations of IL-1β, IL-6 and TNF-α were determined by multiplex immunoassay." (PMID 32899224, 2020). "This shift to aerobic glycolysis during Mtb infection is coupled to the ability of human macrophages to produce specific pro-inflammatory cytokines, such as mature IL1β, to lower the burden of infection." (PMID 32477344, 2020). "IL-18, together with IL-1β, serves in activation of downstream inflammation signaling in a state of infection and injury." (PMID 32297262, 2020). "Instead, significant levels of IL-6 and IL-1β responses were observed at 24 and 48 h after infection with SARS-CoV-2, respectively." (PMID 33062077, 2020). "IL-1β is a cytokine that can be produced by macrophages and glial cells and is involved in many aspects of the immune response to infection, including immune regulation of inflammation, adaptive response modulation, and antiviral action." (PMID 33396704, 2020). "In contrast, IL-1β (P = 0.0324, P = 0.0126) and IL-6 (P = 0.0340, P = 0.0077) in lung was significantly lower at 5 days after infection." (PMID 33603716, 2020). "We observed significantly increased IL-1β mRNA levels as well as increased miR-146a expression across all treatments 2 days post infection." (PMID 32117283, 2020). "Infection of P. zopfii GT-II in macrophages upregulated mRNA expression of IL-1β, TNF-α and Cxcl-1 (2 h)." (PMID 31959834, 2020). "The residual caspase-1/11, ASC-dependent and NLRP3/AIM2-independent maturation of IL-1β in response to infection with H37Rv and isolate 411 suggests the involvement of an additional inflammasome sensor in detecting these bacteria." (PMID 32111888, 2020). "Consistent with this, a knockout of MyD88 in THP-1 cells completely abolished the expression of the inflammatory cytokines TNF-α and IL-1β upon infection with C. acnes, L.m., or LPS." (PMID 33178195, 2020). "Primary M1 and M2 macrophages were prepared from patients followed by infection with H. pylori for indicated time periods, which also secreted low levels of mature IL-1β as observed in parental and knockout THP-1 monocytes." (PMID 32230726, 2020). "Duration of shedding was inversely correlated with plasma levels of T‐cell cytokines IL‐1β and IL‐17A at the initial phase of infection, and patients had lower levels of pro‐inflammatory cytokines during intermittent shedding." (PMID 32742654, 2020). "Infection with UV-inactivated MV also induced IL-1β release, although at a lower level comparing with intact MV infection." (PMID 32033013, 2020). "For instance, neutrophil-derived serine proteases and pathogen-released enzymes can also process and activate IL1β, and these processes have important effects during inflammation and infection." (PMID 32751171, 2020). "In samples collected 6 h, 12 h or 24 h after initial infection, we observed pro-IL-1β expression was enhanced during coinfection compared to singly infected samples." (PMID 30794604, 2019). "Whatever the bacterial lifestyle, i.e., planktonic, sessile or biofilm-dispersed, K. pneumoniae induced production of the pro-inflammatory cytokines IL-6, IL-1β, and KC in the lungs as early as 6 h post-infection." (PMID 31583108, 2019). "A series of studies reported the upregulation of proinflammatory cytokines, such as IL-1β, IL-6, IL-12, IL-8, and IL-18, in vvIBDV infection both in vitro and in vivo." (PMID 31632367, 2019). "While all the cytokine levels returned to basal levels in wild-type mice by 2 days post-infection, Foxo3a mice showed sustained expression of IL-1β, CXCl-1, and TNF-α up to 3 days." (PMID 31796819, 2019). "Defensin 1 administration to macrophages 1 h and 5 h after infection with D39 (MOI10) led to a reduction of bacteria-induced release of key inflammatory cytokines such as IL-1β, IL-6, and TNF-α." (PMID 31657264, 2019).
infection (continued). "The expression levels of all cytokines except IL‐1β were significantly lower in lung specimens from KitW‐sh/W‐sh mice than those from WT mice 24 hours post‐infection." (PMID 30729611, 2019). "Our reverse transcription-polymerase chain reaction (RT-PCR) analysis revealed that ZFP36L1 was specifically upregulated by IL-1β treatment or infection of Ad-HIF-2α or Ad-ZIP8 in primary-culture chondrocytes." (PMID 30622281, 2019). "P2X7 receptor activation in vivo before infection decreased the release of IL-1β into the mouse peritoneum and prevented effective control of the infection as the bacterial load in the blood increased in animals pre-treated with ATP." (PMID 31221993, 2019). "In the liver, the three reference genes were validated against TNF-α and IL-1β during chronic stages of infection with F. hepatica and in uninfected controls." (PMID 30728395, 2019). "Strikingly, we observed that three major inflammatory cytokines (IL-6, TNF-α, and IL-1β) were produced less during infection in AIC than in LCC." (PMID 31801841, 2019). "When infection experiments were performed in the presence of A151 and glyburide administered in conjunction, the production of IL-1β was completely abrogated." (PMID 32038610, 2019). "MNV-infected macrophages that were primed with the TLR2 agonist Pam3CSK4 secreted IL-1β into the culture supernatant starting 12–16 hours post-infection." (PMID 31017981, 2019). "Pro-inflammatory cytokines (including IL-1β, IL-6, and IL-8) are necessary to initiate the inflammatory response during infection." (PMID 31616382, 2019). "In this study, we investigated the role of ERS in mitochondrial damage and IL-1β production in macrophages during infection with a virulent M. bovis strain." (PMID 30846986, 2019). "Interleukin-1β (IL-1β) is a potent, pro-inflammatory cytokine of the innate immune system that plays an essential role in host defense against infection." (PMID 31019507, 2019). "Conversely, a report in 2011 indicated that IL1β and caspase 1 were required for effective C. pneumoniae clearance in mice, reporting observations of increased infections and pathology in caspase 1-defective mice." (PMID 31415633, 2019). "At 4 hours post-infection (hpi), IL-1β released into the supernatant was detected by ELISA, and the response of cells from individual human donors was compared (each dot represents a unique donor)." (PMID 31449558, 2019). "The proinflammatory cytokines TNF-α, IFN-γ, IL-1β, IL-2, IL-5, and IL-6 also showed high levels of expression during the infection period, suggesting that the balance between cytokines determines the course of infection." (PMID 31636507, 2019). "Our prior research has demonstrated that the intracellular parasite Toxoplasma gondii induces IL-1β release from primary human monocytes during infection." (PMID 31449558, 2019). "Dam 2 had an increase in IL-1β, IL-2, IL-6, IL-7, IL-12, IL-15, IL-16 and IL-17A, peaking on day 14 post-infection for all but IL-12 and IL-15 which peaked on day 7 post-infection." (PMID 30657788, 2019). "A/J C5+/+ mice had higher levels of liver IL-10, IL-1β, IL-12p40, and IL-12p70 and kidney IL-1β, IL-12p40, and IL-12p70 on the sixth day of infection than A/J C5−/−." (PMID 31687410, 2019). "In our study, both IL-1β and IL-18 significantly increased during infection with vvIBDV, which was in accordance with the inflammation detected by histopathological analysis." (PMID 31632367, 2019). "These divergent effect patterns suggest that nga(G330D) infection drive IL-1β release through a different pathway as compared to ATP, which is also in line with our other findings presented here." (PMID 31275321, 2019). "In fact, it is rational to suppose that TNF-α and IL-1β produced at the infection primary foci explain the hyperalgesia observed before spinal cord glia activation." (PMID 31138231, 2019).
infection (continued). "Interleukin-1 beta is a proinflammatory cytokine which is secreted by monocytes and macrophages and play a pivotal role in the innate immune response to infection." (PMID 30728751, 2019). "Two weeks after challenge infection (D42), the IL-1β concentration in BAL fluid was significantly higher in group Lipo_DDA:TDB compared to the PCG and group SWE_TLR (P ≤ 0.05)." (PMID 31703726, 2019). "Interleukin-1β (IL-1β) is an important immune signaling cytokine responsible for inflammation and has been previously shown to contribute to disease severity in numerous infections." (PMID 30794604, 2019). "In the immunocompetent mice, the Chr6ABB strain induced significantly less CCL3, CXCL1 (KC), IL-1β, IL-17A, and the p19 subunit of IL-23 in the oral tissues relative to the progenitor strain after 1 day of infection." (PMID 31091232, 2019). "Inflammasome activation and IL-1β production are also differentially regulated depending on the nature of the stimulus, which can be as diverse as pathogen infection, microbial products, or sterile inducers of inflammation." (PMID 31449558, 2019). "IL-1β production was reduced by more than 75% in caspase-1−/− bmDCs (p < 0.01), indicating that it is essential for maturation of IL-1β following infection by both strains." (PMID 31262357, 2019). "The mature form of IL-1β (activated by pathogen infection) recruits neutrophils, thereby priming macrophages to eradicate pathogens." (PMID 29976843, 2019). "Following infection, cytokines, such as IL-1β, IL-6, TNF-α, and inducible nitric oxide synthetase (i-NOS), that coordinate immune/inflammatory responses are triggered and activated." (PMID 30814582, 2019). "Together these data suggest that Syk signaling is critical for production of IL-1β and NLRP3 transcripts in T. gondii-infected primary human monocytes, and therefore appears to act in the priming stage of IL-1β production during infection." (PMID 31449558, 2019). "Infection with S. Typhimurium triggered the highest expression of IL1β (317-fold compared to uninfected cells), CXCLi1 (121-fold), and CXCLi2 (225-fold) of the three different serovars, in particular, substantially higher than S. Gallinarum infection." (PMID 31998655, 2019). "In the CNS of Ifnar1−/− mice, IFN-α1, IFN-β, TNF, IL-1α, IL-1β, and IL-6 mRNA levels were increased at day 4 post infection when compared with sham-injected controls." (PMID 31511023, 2019). "Since neutrophils are strongly recruited to the infection site in the presence of IL-1β, we aimed to address their function and effects on bacterial colonization and biofilm formation." (PMID 31156635, 2019). "The current work provides experimental evidence of the activation of IL-1β synthesis and secretion during vascular leakage in DENV-associated infection and identifies IL-1RA as a potential agent for the prevention and treatment of this infectious disease." (PMID 31824450, 2019). "Inflammasome activation by infection with C. perfringens was examined by immunoblot analysis using anti-caspase-1 and anti-IL-1β, as well as by ELISA for IL-1β." (PMID 31708887, 2019). "A recent study demonstrated that mutation of the SPI-1 T3SS resulted in decreased HMDM cytotoxicity and IL-1β release, while infection with ΔSPI-2 S." (PMID 31402916, 2019). "Myeloid cells, such as macrophages and monocytes, are major producers of IL-1β during infection or injury." (PMID 31449558, 2019). "IL-1β and IL-6 demonstrated variable regulation after infection with live compared to heat-inactivated V. cholerae." (PMID 31434744, 2019). "The results showed that infection of macrophages with the ∆stir-2 mutant increased the expression of IL-6, IL-1β, and TNF-α at 18, 24, and 48 hpi compared with macrophages infected with the wild-type SC09 strain or the ∆stir-2 + pSTIR-2 mutant strain." (PMID 31500298, 2019).
infection (continued). "The serum IL-1β levels were markedly increased both at 4 h and 8 h post infection as compared with vehicle, suggesting that evodiamine had promoted NLRP3 activation in the mouse model." (PMID 30971927, 2019). "Infection with the ∆stir-2 mutant increased the expression of IL-6, IL-1β, and TNF-α at 18, 24, and 48 hpi, respectively, compared with macrophages infected with the wild-type SC09 strain or the ∆stir-2 + pSTIR-2 mutant strain." (PMID 31500298, 2019). "In this regard, the significance of Pseudomonas-induced ceramide-enriched lipid platforms, will be of interest; having critical roles in pathogen internalisation, NF-κB activation and IL-1β transcription in response to the infection." (PMID 30978238, 2019). "Other authors have previously confirmed the role of IL-1β and IL-1R in the recruitment of neutrophils to the infection site." (PMID 31824481, 2019). "High concentrations of NAM did inhibit IL-1β release upon infection with both wt and nga(G330D) bacteria." (PMID 31275321, 2019). "When functional Il-1β was blocked using a well-characterized and validated il-1β morpholino, the morphants showed significantly increased infection compared with control morphants." (PMID 30552162, 2019). "Accompanying increased production of IL-1β, the percentages of neutrophils (CD11b+ Ly-6G+) in the blood of evodiamine group were significantly increased at 4 h post infection as compared with those in vehicle group." (PMID 30971927, 2019). "Transcript expression of IL-1β and IL-8 were reduced upon Defensin 1 administration and concomitant infection." (PMID 31657264, 2019). "In this study, using the zebrafish M. marinum model and fluorescent transgenic lines, we show that il-1β is transcriptionally upregulated in macrophages early during in vivo infection." (PMID 30552162, 2019). "Inflammation or infection of the placenta induces a robust signaling response, including increased concentrations of IL-1β, IL-6, IL-8 and TNF." (PMID 31537532, 2019). "We also observed a decrease in IL-1β secretion at 48 h post-infection consistent with a defect in inflammasome activation." (PMID 30796268, 2019). "To determine the role of caspase-1 and NLRP3 in IL-1β secretion by B. abortus-infected LX-2 cells, we performed the infection of LX-2 cells in the presence of specific pharmacological inhibitors." (PMID 32038610, 2019). "A possible explanation for the observed differences in IL-1β release is a selective or increased intracellular degradation of IL-1β during wt compared to nga(G330D) infection." (PMID 31275321, 2019). "Our recent work also showed pro-inflammatory cytokines IL-1β and TNF-α to be activated in response to pathogenic infections in ayu." (PMID 29976843, 2019). "Tumor necrosis factor alpha (TNF-α) and interleukin-1β (IL-1β) levels were highly induced following infection with the WT strain compared to infection with strain ΔanvM." (PMID 31337721, 2019). "NCF1-defective mice infected with Mycobacterium marinum demonstrated increased infection loads compared to wild type mice, which also resulted in increased IL1β activity." (PMID 31415633, 2019). "Similar to IL-8, IL-1β is essential for host response and provides protection following infection and injury." (PMID 31658740, 2019). "Such pathways are activated either by mono- or polymicrobial infections, resulting in an increase in the expression of proinflammatory molecules such as IL-6, IL-8, IL-1β, and TNF-α." (PMID 31049022, 2019). "For cytokines, in the ileal mucosa, AH02LA infection markedly up-regulated (p < 0.05) gene expression of IL-1β, IFN-γ, and TNF-α." (PMID 31195631, 2019). "In particular, the production of IL-1β and IL-6 was reduced in the groups treated with UA compared with the infection group, and the expression of IL-10 and IL-12 was significantly increased in T. gondii-infected cells treated with UA." (PMID 31075881, 2019).
infection (continued). "aureus coinfected mice with neutralizing anti-IL-17A or anti-IL-1β antibodies through the first two weeks infection." (PMID 31107882, 2019). "Regardless diet, a clear peak in the response to infection was observed at 48 h with il1β, cox 2, m2cr, c3zeta, mcsf1r1, hsp70, dicent and mif up-regulation than those registered at all sampling times." (PMID 31118462, 2019). "Our data showed that PRV AH02LA infection upregulated specific cytokines expression, such as IL-1β, IFN-γ, and TNF-α in the ileum and IL-1β, IL-10, IFN-γ, and TNF-α in the colon." (PMID 31195631, 2019). "During infection, pyroptosis damages the intracellular replication niches of pathogens, promotes the release the pro-inflammatory cytokines, such as IL-1β and TNFα, and triggers inflammation." (PMID 30858838, 2019). "We found significantly high levels of IFN-γ and IL-1β in αIFNAR1 treated mice while low levels were observed in Isotype mice at 21 days post-infection." (PMID 31801478, 2019). "Susceptible sheep, on the other hand, usually present higher mRNA levels of TNFα and IL1β in the gut mucosa and respective lymph nodes, at the early and late infection." (PMID 31815153, 2019). "The observed up-regulation of IL-1β and IL-8 after infection with A. salmonicida or inoculation with formalin killed A. salmonicida indicates a canonical macrophage innate immune response." (PMID 31231379, 2019). "IL-1β is found in infected cells and VD elevates IL-1β levels in macrophages during infection through direct transcription mechanism." (PMID 31205940, 2019). "A/J C5+/+ mice had higher levels of liver IL-10, IL-1β, IL-12p40, and IL-12p70 and kidney IL-1β, IL-12p40, and IL-12p70 on the sixth day of infection when compared to A/J C5−/− mice." (PMID 31687410, 2019). "At 12 h after the infection, interferon-gamma, interleukin-10, interleukin-17A, interleukin-1 beta, interleukin-6, and tumor necrosis factor alpha (TNF-α) tended to be suppressed with micafungin treatment in both PF and control mouse models." (PMID 31249356, 2019). "Most of the pro-IL-1β+ CD11b+ cells during early infection showed surface marker staining consistent with neutrophils (CD45+ CD11b+ Ly6Ghi Ly6Cint)." (PMID 31107882, 2019). "Y. pestis is known to be able to suppress the production of inflammatory cytokines IL-1β to promote its infection process." (PMID 31069175, 2019). "During early infection with EV71 in mice, brain tissue from NLRP3-inflammasome-deficient showed decreased levels of IL-1β." (PMID 30858838, 2019). "The production of IL1β by inflammasomes during infection with Mtb is critical for a protective host immune response." (PMID 30728749, 2019). "In the current study, the release of the inflammatory cytokines IL-6, TNF-α, IL-1β, and IL-12 in the serum of the TG mice was reduced compared with that of the WT mice after infection with S. Typhimurium or administration with LPS." (PMID 31379864, 2019). "Infection of mice with S. aureus-induced an early inflammatory cytokine response with high levels of IL-1α, IL-1β, IFN-β, TNF-α, IL-6, IL-12p70, IL-27, and IFN-γ in the spleen detected for up to 12 h pi compared to PBS-treated mice." (PMID 31134074, 2019). "Silveira (C. posadasii) infected mice demonstrated an increase in proinflammatory cytokine IL-1β at day 1 post infection and immunoregulatory cytokine IL-10 at day 5 post infection compared to other strains." (PMID 31572393, 2019). "IL-1β and TNFα are central cytokines in immune cell communication and activation and as such recruit innate immune cells to the site of infection and cell damage." (PMID 31273197, 2019). "The levels of inflammatory mediators associated with airway inflammation, including IL-1β, TNF-α, IFN-γ, and IL-6, were also clearly elevated in BALF at 3, 5, and 7 days post HAdV-3 and HAdV-7 infection." (PMID 30626350, 2019).